IGHV1-69 (immunoglobulin heavy variable 1-69)
Description:
V region of the variable domain of immunoglobulin heavy chains that participates in the antigen recognition. Immunoglobulins, also known as antibodies, are membrane-bound or secreted glycoproteins produced by B lymphocytes. In the recognition phase of humoral immunity, the membrane-bound immunoglobulins serve as receptors which, upon binding of a specific antigen, trigger the clonal expansion and differentiation of B lymphocytes into immunoglobulins-secreting plasma cells. Secreted immunoglobulins mediate the effector phase of humoral immunity, which results in the elimination of bound antigens. The antigen binding site is formed by the variable domain of one heavy chain, together with that of its associated light chain. Thus, each immunoglobulin has two antigen binding sites with remarkable affinity for a particular antigen. The variable domains are assembled by a process called V-(D)-J rearrangement and can then be subjected to somatic hypermutations which, after exposure to antigen and selection, allow affinity maturation for a particular antigen.
Synonyms: IGHV1-E; IGHV169; IGHV1E
Tractability: Antibody: its Gene Ontology location is reachable by antibodies, with high confidence; UniProt places it where antibodies can reach, with medium confidence; UniProt predicts a signal peptide or a membrane-spanning region.
Gene: Immunoglobulin variable (V) gene on chromosome 14 (106,714,684 to 106,715,181, reverse strand). Ensembl gene ENSG00000211973.
Subcellular location: Secreted; Cell membrane
Pathways (Reactome):
Immune System: Antigen activates B Cell Receptor (BCR) leading to generation of second messengers; CD22 mediated BCR regulation; Classical antibody-mediated complement activation; FCERI mediated Ca+2 mobilization; FCERI mediated MAPK activation; FCERI mediated NF-kB activation; FCGR activation; Fc epsilon receptor (FCERI) signaling; Immunoregulatory interactions between a Lymphoid and a non-Lymphoid cell; Initial triggering of complement; Regulation of Complement cascade; Regulation of actin dynamics for phagocytic cup formation; Role of LAT2/NTAL/LAB on calcium mobilization; Role of phospholipids in phagocytosis
Disease: FCGR3A-mediated IL10 synthesis; FCGR3A-mediated phagocytosis; Potential therapeutics for SARS
Hemostasis: Cell surface interactions at the vascular wall
Vesicle-mediated transport: Scavenging of heme from plasma
Gene Ontology:
Molecular function: antigen binding
Biological process: immune response; immunoglobulin mediated immune response
Cellular component: extracellular region; plasma membrane
Homologues: Orthologues: mouse Ighv1-74 (67% identical), mouse Ighv1-50 (66% identical), mouse Ighv1-53 (66% identical), mouse Ighv1-55 (66% identical), mouse Ighv1-64 (66% identical), mouse Ighv1-81 (66% identical), mouse Ighv1-61 (65% identical), mouse Ighv1-69 (65% identical), mouse Ighv1-80 (65% identical), mouse Ighv1-4 (64% identical), mouse Ighv1-52 (64% identical), mouse Ighv1-77 (64% identical), and 47 more. Paralogues in human: IGHV1-69D (99% identical), IGHV1-18 (81% identical), IGHV1-3 (81% identical), IGHV1-2 (79% identical), IGHV1-46 (78% identical), IGHV1OR15-1 (78% identical), IGHV1-45 (77% identical), IGHV1-58 (76% identical), IGHV1-24 (75% identical), IGHV1-69-2 (73% identical), IGHV1OR21-1 (73% identical), IGHV1OR15-9 (72% identical), and 65 more.